HLA-G (major histocompatibility complex, class I, G)
Diseases named in the same sentence as HLA-G in open-access papers (continued):
Sharing a sentence is not in itself a finding about the gene and the disease.
tumor (continued). "These authors showed about 50% of positive- tumor cells for HLA-G expression and suggested that induction of HLA-G protein contributed to the modulation of immune responses observed in HL since HLA-G expression correlated with a better prognosis." (PMID 29285306, 2017). "In contrast to normal conditions in which the expression of HLA-G is very restricted to few tissues, ectopic HLA-G expression is common in pathological situations such as cancer, and favors the tumor escape from the patient’s immune surveillance." (PMID 28045999, 2017). "Of note, the only HLA‐G‐positive area of patient 4's tumor corresponds precisely to intracytoplasmic hyaline globules." (PMID 28815885, 2017). "Based on a mouse model it has been shown that HLA-G-positive tumor cells develop and tolerize the host antitumor immune response in vivo." (PMID 27999823, 2016). "The main mechanisms for the tumor escape mediated by HLA-G were an expansion of blood myeloid-derived suppressor cells (MDSCs), loss of peripheral CD4+ and CD8+ T cells, and a cytokine profile in favor of Th2 versus Th1/Th17." (PMID 27999823, 2016). "Tumour cells express HLA-G to escape to immunity and high levels of soluble HLA-G (sHLA-G) have been related with unfavourable outcome of prognosis." (PMID 26862036, 2016). "Here, comparable results were obtained with approximately 25 % of the cases having expression of HLA-G in the primary tumor and 11 % in the metastatic LNs." (PMID 27895918, 2016). "HLA-G immune checkpoint plays a role in maintaining immune tolerance at the fetal-maternal interface, and was shown to participate in tumor immune escape." (PMID 27577073, 2016). "In the last two years, several papers have addressed the role of HLA-G in tumor progression or have characterized this molecule as prognostic factor for the clinical outcome of cancer patients." (PMID 27652273, 2016). "At the site of the primary tumor, we observed 33 and 31 % expression of HLA-E and HLA-G, respectively." (PMID 27895918, 2016). "In tumor cells, hypoxia was previously shown to induce expression of HLA-G gene, an immune checkpoint gene whose function is involved in immune evasion." (PMID 27577073, 2016). "The xenotumor model involves the injection of human tumor cells (M8) transfected with HLA-G subcutaneously in immunocompetent mice." (PMID 27999823, 2016). "Soluble HLA-G is secreted by both tumor cells and cells of the immune system, such as monocytes, T cells, and dendritic cells, and it is conceivable that sHLA-G levels can be used as a diagnostic tool to distinguish benign from malignant tumors." (PMID 27999823, 2016). "We have previously demonstrated that soluble (s)HLA-G concentration is higher in plasma samples from NB patients than in controls, and sHLA-G can be released by NB cells themselves, or by monocytes (stimulated by soluble factors secreted by tumor cells)." (PMID 27610393, 2016). "With the use of this model it was demonstrated that human tumor cells expressing HLA-G can grow in an immunocompetent host and that it affects both the innate and the adaptive immune system." (PMID 27999823, 2016). "They analyzed tumors by tissue microarray for the presence of Foxp3+ cells (Tregs) and tumor expression of HLA-E and HLA-G." (PMID 27652273, 2016). "In agreement, using a xenotumor model or syngeneic tumor cells in mice, it has been reported that HLA-G is involved in tumor immune surveillance in vivo." (PMID 27577073, 2016). "In this context, it is noteworthy that a cellular translocation of HLA-G from APCs to activated T cells and from tumor cells to T/NK cells has been reported." (PMID 27199995, 2016). "Immune cells exposed to HLA-G+ tumor cells overexpress ILT2 at their cell surface, leading to an increased interaction between HLA-G and ILT2, thus further promoting the inhibition of the cytotoxic and allogeneic responses." (PMID 26460949, 2015).
tumor (continued). "The release of soluble HLA-G by malignant cells induces a tumor microenvironment that inhibits the antitumor response and promotes tumor progression." (PMID 26460949, 2015). "We first confirmed that our modified tumor cell lines expressed HLA-G and that our NK line expressed its receptor ILT2." (PMID 26460949, 2015). "When the decreased expression of classical HLA molecules is accompanied by an increased expression of immunomodulatory molecules such as HLA-G, the effective cytototoxic immune response against tumor cells is much impoverished [reviewed at Ref." (PMID 25699038, 2015). "If tumor cell expresses HLA-G, the cytotoxic activity of both T and NK cells are inhibited, facilitating tumor cell spread." (PMID 25699038, 2015). "The same group showed that HLA-G not only impairs NK cells, but it also triggers tumor metastasis via the up-regulation of MMP15." (PMID 26460949, 2015). "Recently, studies have provided evidence that the tolerogenic protein HLA-G shows aberrant expression in a variety of cancers, and it has been suggested that this is a mechanism for tumor escape from immunosurveillance." (PMID 25351636, 2015). "Studies have shown that HLA-G is detected in tumor tissue but rarely in normal tissue, suggesting its specific association with tumor growth and progression, for example by suppressing immune regulation, similar to maternal immune tolerance." (PMID 26627200, 2015). "HLA-G was also reported to exert its tumor immune escape functions by the mechanism of trogocytosis." (PMID 25887663, 2015). "The meanings of such exchanges remain to be explored in depth, but already the interest for the tumor of transferring HLA-G between its constituent cells can be envisioned." (PMID 25887663, 2015). "After interaction with its main receptor ILT2, HLA-G blocks the activation of NK and cytotoxic T cells as well as their killing activities, conferring the tumor with protection against immune cells." (PMID 26460949, 2015). "HLA-G expression by tumor cells has been shown to be important for the escape of immune surveillance by host T lymphocytes and NK cells." (PMID 25887663, 2015). "HLA-G expression was more frequently observed in tumour lesions with advanced stage, and a poor prognosis." (PMID 25689063, 2015). "We performed experiments aimed at demonstrating that tumor cell lines were trogocytic and capable of acquiring membranes and the membrane-bound molecule HLA-G from other cells, be they allogeneic or autologous." (PMID 25887663, 2015). "Other studies have used a preclinical model to investigate the interactions between HLA-G and the anti-tumor response." (PMID 26460949, 2015). "It is also worth mentioning that HLA-G expression is highly dependent on tumor microenvironment factors, particular when IL-10 and a hypoxic factor are present." (PMID 25351636, 2015). "In several malignant transformations, the expression of HLA-G by tumor cells rises dramatically, rendering them strongly immunosuppressive." (PMID 26460949, 2015). "The HLA-G system plays a critical role in the recognition of tumor antigens and the relevant immune responses against carcinoma." (PMID 24870375, 2014). "Many studies have focused on HLA-G in tumoral processes, highlighting its role in tumor escape from the immune response." (PMID 24839609, 2014). "Weak expression of HLA-G was also significantly related to higher tumor stage (p = 0.008) and more nodal involvement (p = 0.006)." (PMID 24997850, 2014). "Survival was prolonged when tumours expressed HLA-G (P = 0.008) and HLA-G was an independent predictor for better survival (P = 0.011)." (PMID 24987709, 2014). "HLA-G plays a role in tumor escape, through expansion of the population of myeloid-derived suppressor cells and an alteration of the cytokine balance in favor of a Th2 response rather than a Th1/Th17 response." (PMID 24839609, 2014).
tumor (continued). "The resulting rapidly growing tumors create a hypoxic microenvironment which promotes angiogenesis, invasion and metastases, but also induces HLA-G expression on tumor cells." (PMID 24800261, 2014). "HLA-G expression after IFN treatment has also been demonstrated in several tumor models, including a melanoma cell line." (PMID 24839609, 2014). "Conversely, HLA-G expression on transformed cells (tumor cells and virus-infected cells) provides them with an immune escape mechanism, avoiding the recognition and lysis by cytotoxic immune effectors, such as NK cells and cytotoxic T lymphocytes." (PMID 25202308, 2014). "For the past decade, HLA-G has been described as a tumor-escape mechanism favoring cancer progression, and blocking strategies have been proposed to counteract it." (PMID 24800261, 2014). "HLA-G is more often expressed in high grade tumours; therefore, it is thought that HLA-G plays a role in tumour growth and aggressive behaviour of high grade EOC." (PMID 24987709, 2014). "A multivariable analysis was performed for OS and DFS using the following parameters: age, TNM stage, tumor grade, adjuvant therapy, circumferential margin, HLA class I expression status, HLA-G expression status and Foxp3+ tumor infiltration." (PMID 24997850, 2014). "Loss of HLA Class I tumor expression was related to a better prognosis in CRC in most studies and HLA-E and HLA-G tumor expression has been correlated with a poor prognosis and tumor progression." (PMID 24997850, 2014). "In this phase, HLA-G expression would enable a proportion of tumor cells to evade the host immune response." (PMID 24800261, 2014). "Results showed that human or murine tumor cells expressing HLA-G can grow in an immunocompetent host and that blocking HLA-G function by a specific antibody inhibits the development of the tumor." (PMID 24800261, 2014). "Recently, the development of animal models established the proof of concept that an HLA-G+ tumor cell can develop and tolerize the host antitumor immune response in vivo." (PMID 24800261, 2014). "HLA-G expression can inhibit NK-cells from lysing tumor cells that have lost or downregulated classical HLA class I expression as a secondary immune escape." (PMID 24997850, 2014). "The feasibility of synthesizing effective HLA-G-derived molecules opens up new possibilities in the fields of tumor diseases and infection." (PMID 24839609, 2014). "In tumor cells or virus-infected cells, the neoexpression of HLA-G shall be highly undesirable due to the inhibition of the immune response." (PMID 24204558, 2013). "It is therefore conceivable that different mechanisms contribute to HLA-G production in human NB, i.e., instruction of other cell types by primary tumor cells and direct production of HLA-G by metastatic NB cells." (PMID 23805414, 2013). "Since most tumour infiltrating microglia/macrophages are found at the border of the ischaemic area, hypoxic stimuli enhance the expression of the HLA-E and HLA-G-immune modulatory molecule as far as it induces M2 polarization." (PMID 24093459, 2013). "By now, involvement of LIR-1 in protecting the fetus from abortion has become common immunological knowledge, and so has the adoption of this mechanism by tumor cells by expressing the LIR-1 ligand HLA-G." (PMID 22844324, 2012). "More recently, some studies have suggested that HLA-G plays an important role through the immune system in tumor development and progression." (PMID 22440091, 2012). "The tolerogenic protein HLA-G has shown aberrant expression in a variety of cancers, which has been suggested as a mechanism for tumor escape from immunosurveillance." (PMID 23265140, 2012). "The BM-infiltrating GD2 positive cells also expressed HLA-G, a monomorphic HLA class Ib molecule, over-expressed in a wide variety of human cancers, endowed with tolerogenic properties facilitating tumor escape from host immune response." (PMID 22253825, 2012).
tumor (continued). "HLA-G re-expression has been suggested as a mechanism of viral and tumor escape from immunosurveillance." (PMID 23265140, 2012). "The distribution of HLA-G is mostly limited to foetal trophoblastic tissues and some tumour tissues." (PMID 23002136, 2012). "In contrast, we observed a significant increase in levels of methylation in tumor samples at CpG sites located in proximity to a hypoxia response element located 243 bp upstream of the HLA-G transcriptional start site." (PMID 18498645, 2008). "Conversely, genes related to epithelial differentiation and keratinization (FLG, FLG2, HRNR, TCHH, KRT73), immune regulation and tumor suppression (HLA-G, UNC5D), and metabolic signaling were downregulated, reflecting loss of tissue integrity and immune control." (PMID 41900972, 2026). "Thus, the HLA-G/LILRB1 axis is an important immune checkpoint not only in tumor biology but also in transplant settings." (PMID 41562090, 2025). "Additionally, T cells acquire immune-suppressive molecules, such as HLA-G and PD-L1, to create the tumor microenvironment." (PMID 39741180, 2025). "In certain cancers, the absence of HLA-G expression is associated with better clinical outcomes, as it makes tumor cells more susceptible to lysis induced by NK cells." (PMID 41234446, 2025). "KIR2DL4 can interact with its ligand HLA-G, which is often overexpressed in tumor cells." (PMID 40549069, 2025). "Additionally, ectopic expression of HLA-G has been observed in various pathological states, such as tumor." (PMID 40549069, 2025). "The immune checkpoint molecule human leukocyte antigen G (HLA-G) also mediates tumor immune escape." (PMID 41019982, 2025). "The tolerogenic features that ensure maternal-fetal immune success were subsequently found to have profound implications for tumor biology, transplantation, and infection, with HLA-G emerging as a central regulator of cytotoxic effector functions across these settings." (PMID 41445738, 2025). "Interestingly, we observed that the history of neoplasm also influenced LEV HLA-G content, especially in the nevi group." (PMID 41268555, 2025). "Also, this is the first study that analyses the influence of previous neoplasm on LEVs release and HLA-G forms." (PMID 41268555, 2025). "Notably, HLA-G can be transferred from malignant PCs to T cells via trogocytosis, thereby impairing anti-tumor immunity." (PMID 40948764, 2025). "In addition, the relevance of this immunosuppressive molecule in ccRCCs has already been demonstrated, and, in analogy to HLA-G, there are already mAbs against this tumor immune checkpoint for anti-tumor therapies." (PMID 40699665, 2025). "In addition, a statistically significant, weak positive correlation was observed in the different RCC subtypes and kidney specimen with the proliferation marker CXCR4 as well as with the two tumor immune checkpoint molecules HLA-G and LGALS9." (PMID 40699665, 2025). "In TNBC mice, the silencing of IDO-1 or injection of the HLA-G antibody could rescue NK cell function, which in turn inhibits tumor growth." (PMID 40303301, 2025). "Also, lung cancer cells have been shown to reduce the surface expression of MHC class I and tumor antigens (human leukocyte antigen-G (HLA-G), thereby enabling immune evasion." (PMID 41023740, 2025). "Human leukocyte antigen G (HLA-G) can induce tumor immune escape, facilitating tumor progression." (PMID 41268555, 2025). "Mechanistically, this immunosuppressive function of HLA-G has been partially shown to operate by inhibiting the cellular anti-tumor immune response and tumor cell killing through its interaction with receptors ILT2, ILT4, and KIR2DL4 expressed on cytotoxic T cells and NK cells." (PMID 39469714, 2024). "Furthermore, interaction of HLA-G on the surface of tumor cells with LILRB1 on NK cells confers protection against NK cell cytolysis." (PMID 38982045, 2024). "HLA-G, known for immune regulation, displays significant membranous expression in tumor tissues." (PMID 39469714, 2024).
tumor (continued). "Here, by using a ccRCC cellular model, we demonstrate, for the first time, that HLA-G modifies the expression of genes related to tumor development, tumor angiogenesis, mitochondria metabolism and ion channels, in the absence of its known receptors ILT2, ILT4 or KIR2DL4." (PMID 39358558, 2024). "Approximately half of archival tumor samples (48%) had expression of HLA-G by immunohistochemistry." (PMID 39105878, 2024). "These discrepancies in clinical observations point to that the roles of HLA-G in tumor biology may be diverse and complicated." (PMID 38877399, 2024). "The positive association between the expression of pro-inflammatory transcripts and HLA-G may indicate that HLA-G is a counter-regulatory mechanism that follows the intra-tumoral infiltration of tumor-reactive lymphocytes." (PMID 38954689, 2024). "Indeed, the presence of HLA-G-bearing EVs and their effect on T lymphocytes has been described in tumors and consequently proposed as a marker for tumor progression." (PMID 39512342, 2024). "The immune-suppressive function of HLA-G supports its role in tumor development and progression." (PMID 39105878, 2024). "Additionally, HLA-G augments the expression of matrix metalloproteinase, which is a tumor metastasis-related factor, providing greater effects on tumor progression." (PMID 38384647, 2024). "Notably, in our MIBC cohort HLA-G expression on tumor cells was highly expressed in sarcomatoid/rhabdoid tumors that show an increased EMT." (PMID 39469714, 2024). "Along similar lines, in hepatocellular carcinoma, the HLA-G 14bp I/D polymorphism was significantly correlated with tumor development in HBV/HCV( +) cases rather than in the HBV/HCV(-) subset." (PMID 38310272, 2024). "Moreover, the effectiveness of Nb‐TriTE demonstrates promise in mitigating challenges posed by tumor heterogeneity, particularly variations in PD‐L1 and HLA‐G expression." (PMID 39234811, 2024). "Tumor cells were able to deliver HLA-G to effector immune cells." (PMID 38310272, 2024). "However, major limitations for HLA-G-targeted immunotherapy are its inter-patient, inter- and intra-tumor expression heterogeneity." (PMID 39766165, 2024). "Since HLA-G and PD-L1 are immune checkpoints described in tumor cells, we checked whether their expressions on BM-derived EVs isolated from NB patients are mutually associated." (PMID 39512342, 2024). "Considering the involvement of both IDO-1 and HLA-G in feto-maternal tolerance, it is worth exploring whether they cooperate to induce immunosuppression in the context of tumor progression." (PMID 37981615, 2024). "HLA-G is considered as a novel tumor immune checkpoint molecule." (PMID 38427106, 2024). "Notably, the impact of HLA-G tumor cell expression on overall and disease specific survival remained independent of clinicopathological parameters in the multivariable regression analysis." (PMID 39469714, 2024). "It has been shown that HLA-G plays a role in tumor progression and metastasis." (PMID 38877399, 2024). "Based on the results above, purified Nb‐TriTE could effectively bind to PD‐L1 and HLA‐G on tumor cells, as well as CD3 on T cells." (PMID 39234811, 2024). "Human leukocyte antigen G (HLA-G) is known for its immune regulatory properties in the placenta to prevent fetal rejection in pregnant women and (aberrantly) expressed in many tumor entities and at immune-privileged sites to induce immune tolerance." (PMID 39469714, 2024). "Therefore, HLA-G-based therapeutic approaches are on the way to become a hot spot in the field of tumor immunotherapy." (PMID 38310272, 2024). "We found that tumors with basal squamous (Ba/Sq) molecular subtype showed significantly higher HLA-G protein expression on tumor cells compared to tumors with luminal, stroma-rich or neuroendocrine-like molecular subtypes (Kruskal-Wallis test for multiple group comparisons: P=0.004)." (PMID 39469714, 2024).